JAK2 (Janus kinase 2)
Diseases named in the same sentence as JAK2 in open-access papers (continued):
Sharing a sentence is not in itself a finding about the gene and the disease.
tumor (continued). "In CRC, exosomes from tumor cells, rich in circular RNAs, activate TAMs’ NF-κB pathway, leading to IL-6 secretion and triggering tumor cells’ Janus kinase 2 (Jak2)/STAT3 pathway." (PMID 39286635, 2024). "Further examination of gene expression profiles from 84 ESCC tumors identified that the chemokine CCL18 promotes tumor cell proliferation through the JAK2/STAT3 signaling pathway." (PMID 39415846, 2024). "Elevated JAK2 expression was found to enhance tumor cell proliferation, metastasis, and invasion, while its downregulation yielded opposing effects." (PMID 38894865, 2024). "Mechanistically, W. coagulans MZY531 postbiotics inhibit tumor growth through the modulation of the Bax/Bcl-2/caspase-3 and JAK2/STAT3 apoptosis pathways and PI3K/AKT/mTOR and TGF-β/SMAD4 cell autophagy pathways." (PMID 39459634, 2024). "Consistent with previous reports, we found enrichment of sgRNA targeting genes associated with both IFN-gamma signalling (Jak1, Jak2, Ifngr2) and TNF signalling (Tnfrsf1a, Fadd) in tumour cells resistant to CAR-T cell killing." (PMID 39261596, 2024). "The expression levels of Ki-67 and p-JAK2 in tumor tissues were detected by immunohistochemical analysis." (PMID 38872110, 2024). "We detected and confirmed the positive expression of JAK2 by IHC and IF in tumor cells from surgical specimens." (PMID 38974233, 2024). "JAK2 regulates the cell cycle, controls the expression of tumor invasion proteins and anti-apoptotic genes, and plays a vital role in tumor growth, survival, and metastasis." (PMID 39771106, 2024). "Mechanistically, Y-A targets the TNF-α/STAT3 pathway, inhibiting STAT3 and JAK2 phosphorylation, thereby activating apoptotic pathways and suppressing tumor cell growth." (PMID 39056720, 2024). "Differences in the tumor microenvironment (TME) phenotype cause JAK2-mutated and JAK2-wild cancers to be characterized by different immune response landscapes." (PMID 38200372, 2024). "CMTM3 can promote the degradation of EGFR to reduce its expression, activate caspase-3 to induce cell apoptosis, and partially inhibit the JAK2/STAT3 signaling pathway to suppress tumor cell proliferation." (PMID 38223763, 2024). "Studies have unveiled its ability to induce tumor cell apoptosis through the Janus kinase 2 (JAK2)/signal transducer and activator of transcription 3 (STAT3)/cyclin-dependent kinase inhibitory protein-1 (p21) pathway and the JNK1 signaling pathway." (PMID 39684655, 2024). "JAK2/STAT3 signaling contributes to the development of a tumour inflammatory microenvironment that correlates with the occurrence and development of many human cancers." (PMID 38305998, 2024). "Previous studies have shown that Gas6 is able to regulate tumor cell migration and invasion through the JAK2/ERK, SRC, and Akt/GSK-3β/β-catenin pathways." (PMID 39451556, 2024). "The JAK2/p-STAT3 pathway is an important pathway involved in the endogenous expression of PD-L1 (in tumor and immune cells) that promotes cancer progression." (PMID 38872221, 2024). "In contrast to the tumour promotor activity of miR-221, a recent study unveiled that miR-506-3p involved Janus kinase 2 (JAK2) in controlling the STAT3 activity during doxorubicin chemoresistance." (PMID 39679367, 2024). "Single-cell transcriptome analysis also showed the expression of IL-6, gp-130, CRP and JAK2 was lower in tumor tissues compared with normal tissues." (PMID 38881895, 2024). "Oral itacitinib also modestly reduced splenomegaly in a murine model of JAK2 V617F–driven neoplasia relevant to MF though expectedly less than JAK2 inhibitors." (PMID 38380328, 2024).
tumor (continued). "The JAK2/STAT3 signaling pathway plays an important role in increasing tumor metastatic ability and chemoresistance in cancer by promoting epithelial – mesenchymal transition (EMT)." (PMID 39588922, 2024). "According to the literature, G-CSF activates STAT through interaction with JAK2 to promote tumor cell proliferation in several cancers." (PMID 39739128, 2024). "It is worth mentioning that besides an IL‐6/JAK2/STAT3 axis‐dependent induction of a macrophage‐tumor cell crosstalk our study uncovered an EV‐mediated crosstalk between tumor cells and macrophages." (PMID 38031260, 2024). "Recent findings have emphasized the potent oncogenic function of JAK2/STAT3 signaling in tumor invasion and metastasis, emphasizing the inhibition of JAK2/STAT3 pathway as a potential therapy in malignancies." (PMID 38182570, 2024). "IL-6R was weakly corrected with gp130 (r = -0.287, P = 0.006) and JAK2 (r = -0.390, P < 0.001) in tumor tissues, and moderately correlated with gp130 (r = -0.467, P = 0.008) and JAK2 (r = -0.555, P = 0.001) in normal tissues." (PMID 38881895, 2024). "Mechanistically, GSCs-derived IFITM3 causes activation of Jak2/STAT3 signaling and leads to robust secretion of bFGF into tumor environment, which eventually results in enhanced angiogenesis." (PMID 38218875, 2024). "In Pten‐null senescent tumours, the JAK2/STAT3 pathway was activated, resulting in the secretion of CXCL1, CXCL2 and IL‐6, thereby promoting macrophage M2 polarisation." (PMID 39270064, 2024). "This strategy, exemplified with a tumor-targeted IL12 in combination with a JAK2 inhibitor, allowed to abrogate cytokine-driven toxicity without affecting therapeutic activity in a preclinical model of cancer." (PMID 38448543, 2024). "Collectively, JAK2/STAT3/c‐Myc signaling axis activation by RNF122 was indicated to enhance tumor growth." (PMID 39218810, 2024). "Further research has revealed that GZMA interacts with the F2R receptor on the surface of tumor cells, activating the JAK2/STAT1 signaling pathway, inducing tumor cell apoptosis, and T cell-mediated tumor killing." (PMID 37884883, 2023). "These ingredients can potentially decrease the levels of inflammatory cytokines (such as IL-6 and TNF-α), inhibit the expression of tumor-related factors (such as JAK2/STAT3, MMP-9, and vimentin), and increase immune cell activity." (PMID 37742025, 2023). "JAK2 belongs to the Janus Kinases family of protein tyrosine kinases that plays an important role during tumor progression through STAT3 phosphorylation." (PMID 36740668, 2023). "Its mechanism of action is complex, but blocking the JAK2/STAT3 signaling pathway appears to be responsible for its anti-tumor effects." (PMID 36902139, 2023). "Intravenous injection of LDLs promoted tumor growth in the xenograft nude mice, and also increased p-JAK2, p-STAT3, and Ki-67 expression, and downregulated caspase-3 expression." (PMID 37900720, 2023). "Conclusively, SOCS 1 and 3 methylation and its tumour growth suppression activity demonstrate the importance of the constitutive activation of the JAK2/STAT3 pathway in the development of HCC." (PMID 37680708, 2023). "The tumor-promoting effects of IL-17 and its receptor IL-17R are achieved through direct influence on tumor cells via the IL-6/JAK2/STAT3-related pathway." (PMID 37762066, 2023). "Individual colony analysis revealed three distinct tumor subclones, namely JAK2 N533Shet+/CALRtype1het+, JAK2N533Shet+/CALRwt, and JAK2N533Shet+/CALRtype1hom+." (PMID 38239637, 2023). "It was also shown that the WW domain-containing oxidoreductase inhibits tumor growth and metastasis in TNBC by inhibiting JAK2 phosphorylation and impeding the association of JAK2 with STAT3, thereby preventing STAT3 phosphorylation." (PMID 37237509, 2023). "The deactivation of JAK1 and JAK2 signaling led to acquired resistance to IFN‐γ, subsequently causing damage to immune surveillance and tumor cell proliferation." (PMID 37386520, 2023).
tumor (continued). "When scores for tumour cytoplasm and stromal JAK2 were combined, patients high for the marker in both locations had significantly reduced prognosis (HR = 1.550, 95% CI: 1.099–2.187, log rank p = 0.013)." (PMID 37199043, 2023). "Conversely, restoration of SOCS2 expression or inhibition of JAK2/STAT5 signaling can suppress tumor metastasis in HB." (PMID 37955014, 2023). "JAK2 inhibitors have also been shown as a promising strategy for reducing tumour progression in xenografts from patients with HNSCCs." (PMID 36980527, 2023). "Others have demonstrated that JAK2/STAT1 inhibition in combination with enzalutamide decreases the CXCR7-driven CRPC tumor growth." (PMID 37347559, 2023). "The IFNγ-JAK2 signaling pathway in ATC promotes tumor metastasis by regulating the augmented expression of ICAM1 and PD-L1." (PMID 37345200, 2023). "That’s caused by an important mechanism of immune escape involving tumor cells’ defects in the IFNγ receptor kinases JAK1 and JAK2 and the signal transducer and activator of transcription (STAT) molecules." (PMID 37100920, 2023). "Several studies indicate that B7-H3 overexpression inhibits the apoptosis of tumor cells via inadequate activation of the JAK2/STAT3 pathway." (PMID 37110590, 2023). "JAK2, in addition to having a mutation that is present in many cancers, is downregulated in tumor cells; JAK2 was up and then downregulated by similar magnitudes before not being observed to have statistically significant fold changes." (PMID 37873786, 2023). "Honokiol, a herbal constituent that possesses various anti-tumor and anti-angiogenesis properties, was found to inhibit tumor sphere formation in oral CSC-like OSCC cells by impeding the JAK2/STAT3 pathway activity." (PMID 38170015, 2023). "It has been found that gastric cancer-associated MSCs, by secreting IL-6 and IL-8 cytokines, as well as the JAK2/STAT3 signaling pathway, have caused the polarization of macrophages towards M2 macrophages, which promotes tumor growth." (PMID 38022534, 2023). "Mechanistically, we not only observed activation of the JAK/STAT pathway in EC tissues, but also demonstrated that LDLs promoted EC cell proliferation, migration, and invasion, as well as tumor growth by upregulating the phosphorylation of JAK2 and STAT3." (PMID 37900720, 2023). "It was found that naringenin can not only activate the caspase-9/caspase-3/PARP/C-PARP apoptosis pathway but also inhibit tumor cell proliferation and growth via the inhibition of JAK-2/STAT-3." (PMID 37298981, 2023). "These are characterized by calreticulin (CALR), myeloproliferative leukemia virus proto-oncogene (MPL) and the tyrosine kinase Janus kinase 2 (JAK2) mutations, eventually establishing a hyperinflammatory tumor microenvironment (TME)." (PMID 36910610, 2023). "We compared these data to the SCC16-0016 (JAK2-mutant) tumor dissociate, and as expected the tumor cells in this metastatic lesion did not express MHC-I or PD-L1." (PMID 36934113, 2023). "CCL2 influences tumor vascularization and metastasis by targeting vascular endothelial cells through the Janus kinase 2 (JAK2)-STAT5 and p38 mitogen-activated protein kinase pathways." (PMID 37373025, 2023). "-Promotes EMT of HCC tumour cells via JAK2/STAT3/Snail signalling pathway and hence induces their migration and invasion." (PMID 37894344, 2023). "It has been reported in tumor diseases and endocrine diseases that the JAK2/STAT3 pathway can induce the macrophages transformed to M2 type." (PMID 35079347, 2022). "JAK2/STAT3 can induce systemic inflammatory response and is associated with the occurrence of tumor cachexia." (PMID 36591515, 2022). "Many natural compounds affect tumor progression by suppressing activation of pathways involved in cell growth and proliferation, such as the JAK2/STAT3 pathway." (PMID 35116094, 2022). "IL-6/JAK2/STAT3 pathway has considerable potential in inhibiting tumor growth and restoring anti-tumor immunity." (PMID 36591515, 2022).
tumor (continued). "This is in line with previous reports showing that downmodulation of JAK1 and JAK2, both essential tyrosine kinases in the IFNγ-signaling pathway, in tumor cells results in resistance to CD3 bsAbs." (PMID 36271507, 2022). "In the present study, the GZMA-F2R communication promoted JAK2/STAT1 signal-induced tumor suppression both in vitro and in vivo." (PMID 35256589, 2022). "Only the BCOR‐ITD was included in clone 1, whereas three clade mutations (FLT1, JAK2, and MYH7) were additionally detected in relapsed tumor samples (clones 2, 3)." (PMID 34967151, 2022). "We showed higher DTH, increased lymphocyte proliferation, decreased tumor growth and reduced JAK2/STAT3 phosphorylation in mice treated with naringenin and CPT." (PMID 35606804, 2022). "Previous studies have demonstrated that the biological activities of tumor cells are regulated by multiple signaling pathways including the JAK2/STAT3 cascade." (PMID 35116094, 2022). "In preclinical models, it was demonstrated that recombinant human erythropoietin (rHuEPO) protected breast cancer cells against the anti-tumor effects of trastuzumab treatment through the activation of Src facilitated by JAK2 and PTEN inactivation." (PMID 36291900, 2022). "Triptolide-mediated repression of PD-L1 reduced tumor growth of patient-derived tumor xenografts and was mediated via inhibition of JAK2/STAT." (PMID 36700235, 2022). "In vivo, β-Ele and cisplatin synergistically suppressed the tumor growth and induced apoptosis, and down-regulated the expression of p-JAK2 and p-STAT3." (PMID 35909161, 2022). "Together, these results suggested that the GZMA-F2R communication suppressed the tumor by promoting the activation of JAK2/STAT1 signaling pathway." (PMID 35256589, 2022). "Overexpression of SNHG6 represses miR-181a, which in turn induces JAK2 expression and promotes tumor cell proliferation." (PMID 35740344, 2022). "In NPC, IL6 activates JAK2/STAT3 signaling pathway to promote tumor progression, thus affecting the prognosis of patients." (PMID 36506508, 2022). "Several studies reported the downregulation of miR-375 in gastric cancer and its function in inhibiting tumor development by suppressing JAK2." (PMID 35087589, 2022). "The Pax5Prd*‐Jak2/+ tumor cells also downregulated B220 and CD19 expression and had a similar cell surface phenotype as the Pax5Jak2/+ tumor cells." (PMID 35156727, 2022). "Expression levels of the tumor cell–autonomous gene IFNGR1 and downstream signaling axis and effector genes, including JAK1, JAK2, and IRF1, were all significantly lower in PRC2-loss tumors than in PRC2-wt tumors (P < 0.05)." (PMID 35852856, 2022). "In view of the well-defined tumor-suppressing function of SOCS2 by inhibiting Jak2/Stat3 signaling, we detected the effects of miR-877-3p on Jak2/Stat3 signaling in GC." (PMID 35600882, 2022). "A growing body of evidence indicates that the activation of the JAK2/STAT3 signaling pathway by chemokines or cytokines plays a positive role in tumor growth and progression." (PMID 35155249, 2022). "The Jak2 kinase activity is also required for tumor progression, as treatment of Pax5Jak2/+ tumor‐bearing mice with the JAK1/2 inhibitor ruxolitinib delayed tumor growth leading to prolonged survival." (PMID 35156727, 2022). "The IFN-γ and EGFR have used Janus kinase 2 (JAK2) as standard signaling to transmit external or internal signals to tumor cells, respectively." (PMID 37305016, 2022). "In the present study, the GZMA-F2R communication at the LDPRSFLL motif of F2R suppressed tumor progression by promoting the JAK2/STAT1 signal activation-induced apoptosis." (PMID 35256589, 2022). "The Western blot analysis of tumor tissues showed that the β-Ele combined with cisplatin markedly suppressed the expression of p-JAK2 and p-STAT3." (PMID 35909161, 2022). "For example, bone marrow fat cells secrete significant and regulated levels of IL-6, which promotes metastasis of tumor cells through the JAK2/STAT3 signaling pathway." (PMID 35498437, 2022).
tumor (continued). "An in-vivo study reveals that curcumin injected with tumorspheres of lung cancer NCI-H460 cells in nude mice suppressed the tumor growth via repressing the JAK2/STAT3 signaling pathway." (PMID 35883653, 2022). "IL-6/JAK2/STAT3 pathway is more active in CD44+CD24- BC cells than in other tumor types, and inhibition of JAK2 reduces their numbers and prevents xenograft growth." (PMID 36591515, 2022). "The detailed functional annotation revealed that hsa-mir-216a/mir-217 targeted two hub genes (PTEN and JAK2), which act as tumor suppressors in numerous cancers." (PMID 35845108, 2022). "Elevated SIRT6 expression leads to tumor cell apoptosis by upregulating the expression of Bax and cleaved caspase-8, and downregulating Bcl-2, and inhibiting the Janus kinase 2 (JAK2)-STAT3 pathway." (PMID 35463332, 2022). "Phospholipase A2 Receptor 1 (PLA2R1) is a transmembrane protein of the mannose receptor family that can regulate several tumor-suppressive responses via JAK2 activation." (PMID 36106120, 2022). "Solid Tumors: CuI (10 μM) treatment in NIH 3T3 cells led to a reduction in p-STAT3 and p-JAK2, which was confirmed in an array of tumor cell lines." (PMID 36355554, 2022). "The miR-543 expression serves as a tumor suppressor and prevents cell proliferation by targeting JAK2 and STAT3 in hepatocellular carcinoma." (PMID 35087589, 2022). "The tumor-specific component of the ICI resistance was due to genetic loss of IFNGR1/2 and JAK2, and amplification of IFN signaling inhibitors SOCS1 and PIAS4." (PMID 35269844, 2022). "The JAK2/STAT3 signaling pathway plays a key role in mediating multiple effects of IL-6 on tumor cell proliferation, anti-apoptotic, invasion and metastasis." (PMID 35790790, 2022). "Previous studies suggested that the activation of FAK/ERK or JAK2/STAT3 signaling mediated the pro-tumor activities of CKAP2." (PMID 35853854, 2022). "This interaction induced tumor suppression and T cell-mediated killing of tumor cells via the activation of the JAK2/STAT1 signaling pathway." (PMID 35256589, 2022). "The higher expression of JAK2 in PDAC patients was found to be correlated with increased tumor size and lower overall survival." (PMID 36500220, 2022). "Protein levels of p38/JAK2/STAT1 were markedly downregulated in miR-195-5p overexpressed PTC cells/tumor xenografts, whereas circRNA NRIP1 overexpression negated these impacts." (PMID 36230649, 2022). "High glucose environment can induce hepatoma cells to up-regulate the expression of HKDC, which can promote the proliferation, invasion and metastasis of tumor cells by downregulating the HKDC/JAK2/STAT1/caspase-3 signaling pathway." (PMID 35784761, 2022). "Overexpression of PARK2 inhibited tumor growth, invasion, and angiogenesis, probably through suppressing the JAK2/STAT3/VEGF signaling pathway in OS." (PMID 34691358, 2021). "Disruption of JAK2/STAT3/VEGF signalling by overexpression of PARK2 was shown to suppress OS tumour growth and angiogenesis in vivo and to induce OS apoptosis in vitro." (PMID 33382511, 2021). "A lot of evidences suggest that SOCS5 serves as a tumor suppressor in cancers by negatively regulating JAK2/STAT3." (PMID 33935775, 2021). "In tumor tissues from galangin treated mice, the ratios of p-JAK2/JAK2 and p-STAT3/STAT3, as well as the protein expressions of Bcl-2, caspase-3 and Ki67 were all reduced remarkably (p < 0.01 or p < 0.001)." (PMID 33981228, 2021). "This study found that LNT caused a significant increase in miR-216a-5p expression levels in tumor cells; decreased related protein expression in the JAK2/STAT3 pathway." (PMID 34900727, 2021). "They found that JAK2 inhibition prevented tumor PD-L1 expression and that the combination enhanced the CTX NK-mediated killing via ADCC against PD-L1+ HNSCC cells." (PMID 33718169, 2021). "Consistent upregulation of the ALKBH5-HOXA10 loop promoted EOC tumor growth and resistance to cisplatin by activating the JAK2/STAT3 signaling pathway in the m6A-dependent manner." (PMID 34496932, 2021).